P2RY6 (pyrimidinergic receptor P2Y6)
Description:
Receptor for extracellular UDP > UTP > ATP. The activity of this receptor is mediated by G proteins which activate a phosphatidylinositol-calcium second messenger system.
Synonyms: P2Y6
Tractability: Small molecule: a drug acting on it is in phase 2 or 3 trials; a high-quality ligand is known; it belongs to a druggable protein family. Antibody: its Gene Ontology location is reachable by antibodies, with high confidence; UniProt places it where antibodies can reach, with medium confidence; UniProt predicts a signal peptide or a membrane-spanning region. PROTAC: ubiquitination databases record sites on it; a small molecule that binds it is known.
Target class: Purine receptor; Small molecule receptor (family A GPCR); Membrane receptor; Family A G protein-coupled receptor; Nucleotide-like receptor (family A GPCR)
Chemical probes: CHEMBL3220046, CHEMBL3220052
Gene: Protein-coding gene on chromosome 11 (73,264,498 to 73,305,103, forward strand). Ensembl gene ENSG00000171631.
Subcellular location: Cell membrane
Pathways (Reactome):
Signal Transduction: G alpha (q) signalling events; P2Y receptors
Gene Ontology:
Molecular function: G protein-coupled ADP receptor activity; G protein-coupled UDP receptor activity; G protein-coupled UTP receptor activity; protein binding; G protein-coupled receptor activity; G protein-coupled purinergic nucleotide receptor activity
Biological process: cellular response to purine-containing compound; cellular response to pyrimidine ribonucleotide; positive regulation of ERK1 and ERK2 cascade; positive regulation of inositol trisphosphate biosynthetic process; positive regulation of vascular associated smooth muscle cell proliferation; G protein-coupled receptor signaling pathway; phagocytosis; phospholipase C-activating G protein-coupled receptor signaling pathway; positive regulation of release of sequestered calcium ion into cytosol; cellular response to oxygen-containing compound; G protein-coupled purinergic nucleotide receptor signaling pathway
Cellular component: plasma membrane; membrane
Genetic constraint (gnomAD): Loss-of-function variants: 21 observed, 18.83 expected, observed/expected ratio (o/e) 1.12, 90% interval 0.79 to 1.6. The upper end of that interval is the gene's LOEUF score, 1.6, which puts it in group 6 of 6, group 1 being the genes least tolerant of losing a copy. Missense variants: 389 observed, 434.18 expected, observed/expected ratio (o/e) 0.9, 90% interval 0.82 to 0.97. Synonymous variants: 184 observed, 193.66 expected, observed/expected ratio (o/e) 0.95, 90% interval 0.84 to 1.07.
Homologues: Orthologues: chimpanzee P2RY6 (99% identical), macaque P2RY6 (98% identical), dog P2RY6 (93% identical), pig P2RY6 (93% identical), guinea pig P2RY6 (90% identical), rat P2ry6 (88% identical), mouse P2ry6 (87% identical), rabbit P2RY6 (77% identical). Paralogues in human: P2RY4 (39% identical), P2RY2 (38% identical), P2RY1 (34% identical), OXGR1 (30% identical), SUCNR1 (28% identical), HCAR2 (22% identical), HCAR3 (22% identical), FFAR3 (22% identical), GPR42 (22% identical), FFAR2 (22% identical), HCAR1 (22% identical), FFAR1 (21% identical), and 3 more.